TRPC3 (transient receptor potential cation channel subfamily C member 3)
Diseases named in the same sentence as TRPC3 in open-access papers (continued):
Sharing a sentence is not in itself a finding about the gene and the disease.
ovarian carcinoma (15 papers, 2012 to 2025). A malignant neoplasm originating from the surface ovarian epithelium. "Recently, there has been increased interest in TRP channels, which are overexpressed and dysregulated in various carcinomas, such as TRPC3 in ovarian cancer, TRPC6 in hepatocellular carcinoma, TRPM7 in breast cancer and TRPM8 in prostate cancer." (PMID 40813985, 2025). "TRPC3 is a high-calcium permeable cation channel that regulates calcium-dependent signaling pathways involved in the proliferation and metastasis of ovarian cancer." (PMID 38957470, 2024). "This elevated expression of TRPC3 in the plasma membrane promotes cell survival and inhibits apoptosis (programmed cell death) in ovarian cancer cells." (PMID 37845675, 2023). "To further characterize the role of TRPC3 in ovarian cancer, we first detected the expression of TRPC3 in our clinical ovarian cancer samples." (PMID 35869392, 2022). "Our results collectively demonstrate that PLAA inhibits ovarian cancer metastasis via downregulating TRPC3-mediated intracellular calcium level." (PMID 35869392, 2022). "Here, we also found that TRPC3 knockdown inhibited migration and invasion in ovarian cancer cells, whereas TRPC3 overexpression presented the opposite effect." (PMID 35869392, 2022). "Meanwhile, PLAA inhibited metastasis of ovarian cancer by inhibiting transient receptor potential channel canonical 3 (TRPC3)-mediated the intracellular Ca2+ level." (PMID 35869392, 2022). "For example, TRPC3 channel promotes the growth of human ovarian cancer cells, and it can modulate the growth and apoptosis resistance of triple negative breast cancer cells via the TRPC3/RASA4/MAPK signaling pathway." (PMID 35870973, 2022). "Our results together suggest that PLAA inhibits ovarian cancer metastasis in a TRPC3 dependent manner." (PMID 35869392, 2022). "We validated that TRPC3 mRNA were dramatically upregulated in ovarian cancer tissues compared with benign ovarian tumor tissues, and were higher in late stages of ovarian cancer tissues compared with the early stages." (PMID 35869392, 2022). "In human ovarian cancer, the expression of TRPC3 was increased, and injection of TRPC3-knock down SKOV3 cells decreased tumor formation in nude mice." (PMID 32138386, 2020). "Our results and those of previous studies suggest that TRPC3 plays an important role in ovarian cancer." (PMID 32087757, 2020). "In this study, ovarian cancer specimens were also analyzed for transient receptor potential channel C3 (TRPC3) expression; TRPC3 expression levels were higher in ovarian cancer samples than in normal ovarian tissue samples." (PMID 32087757, 2020). "The ovarian tissue samples from the patients with ovarian cancer showed higher protein expression of TRPC3 than the ovarian tissue samples from the uterine fibroid patients." (PMID 32087757, 2020). "Ovarian cancer cells typically display high expression of TRPC3, be they functional or suppressed, because of the Ca2+ increase stimulated by EGF (epidermal growth factor)." (PMID 32785177, 2020). "Previous studies have shown that TRPC3 protein levels are significantly increased in human ovarian cancer specimens compared to normal ovarian tissue samples." (PMID 32087757, 2020). "TRPC3 protein levels are markedly increased in human ovarian cancer specimens compared to normal ovarian tissue specimens, and decreasing the expression of TRPC3 reduces the proliferation of cultured human ovarian cancer cells." (PMID 32087757, 2020). "Two discrete bands, one at around 100 kDa and one located between 140 and 180 kDa, were detected, similar to the reported sizes of TRPC3 in human ovarian cancer cell line SKOV3." (PMID 31003514, 2019). "Accordingly, estrogen enhances the progression of ovarian cancer cells by activating TRPC3." (PMID 35870973, 2022). "We further observed the effect of Ca2+ influx on TRPC3 promoting ovarian cancer metastasis." (PMID 35869392, 2022).
ovarian carcinoma (continued). "TRPC3 is also a regulator of follicle-stimulating hormone, which could be a potential therapeutic target for ovarian cancer." (PMID 35870973, 2022). "Increasing evidence has demonstrated that TRPC3 is involved in a series of physiological activities and plays an important role in tumor proliferation, invasion and migration, including lung cancer, gastric cancer, bladder cancer and ovarian cancer." (PMID 35869392, 2022). "To investigate whether E2 promotes the proliferation of ovarian cancer cells through TRPC3, we detected the expression of TRPC3 in different ovarian cancer cell lines through Western blot and immunocytofluorescence analyses." (PMID 32087757, 2020). "As TRPC3 is inhibited, ovarian cancer cell growth is suppressed." (PMID 32785177, 2020). "In addition, we compared the expression of TRPC3 genes in human ovarian cancer tissue samples from patients with that in normal ovarian tissue samples." (PMID 32087757, 2020). "The TRPC3 protein channel subfamily also seems involved in the evolution of ovarian cancer: it has been shown that a high expression of TRPC3 in human ovarian cancer cells enhanced the proliferation of ovarian cancer cells, while the inhibition of these channels resulted in growth suppression." (PMID 32785177, 2020). "Previous studies have shown that TRPC3 contributes to the progression of human ovarian cancer." (PMID 32087757, 2020). "Moreover, TRPC3 is overexpressed in human ovarian cancer tissues, and its blockade decreases in vitro and in vivo growth of ovarian cancer cells." (PMID 32575381, 2020). "In yet other studies, TRPC3 was reported to contribute to the proliferation of ovarian cancer cells and lung cancer cells; our current findings that the upregulated TRPC3 in MDA-MB-231 plays a positive role in cancer progression are in line with those previous studies." (PMID 31003514, 2019). "Examples of the significance of Ca2+ influx in cancer include the up-regulation of TRPC3 channels in human ovarian cancers, and the ability of TRPC3 knockdown to inhibit growth factor-mediated Ca2+ signaling and cell cycle progression in SKOV3 ovarian cancer cells." (PMID 22666335, 2012). "Here, we employed CD81‐pHluorin to investigate mechanisms of EV release in ovarian cancer (OC) cells and report a novel role for the Ca2+‐permeable transient receptor potential (TRP) channel TRPC3 in EV‐mediated communication." (PMID 38938673, 2023). "TRPC3 acts as an antiapoptotic regulator through the RAS-AT-MAP kinase pathway and is overexpressed in the plasma membrane of ovarian cancer cells." (PMID 37845675, 2023). "We utilized RNA-seq to identify candidates of PLAA downstream targets, and found TRPC3 to be upregulated in ovarian cancer cells with PLAA knockdown and there was a reverse correlation between PLAA and TRPC3 expression in ovarian cancer cells and tissues." (PMID 35869392, 2022). "The epidermal growth factor receptor (EGFR) is critical for proliferation and tumorigenesis in ovarian cancer, with it being reported that EGF activates TRPC3/4/5, thus prompting Ca2+ inflow in HEK293 cells (human embryonic kidney 293 cells)." (PMID 32785177, 2020). "For example, TRPC1, TRPC3 and TRPC6 were proven to be participated in proliferation of multiple types of cancer, including breast caner, ovarian cancer, liver cancer, and brain cancer." (PMID 29463225, 2018). "Additionally, the upregulation of TRPC3 promotes the activation of the PI3K-AKT pathway, which contributes to ovarian cancer progression by enhancing tumour takeover, durability, and advancement." (PMID 37845675, 2023). "Mechanistically, PLAA inhibited METTL3 expression through the ubiquitin-mediated degradation and destabilized TRPC3 expression via METTL3-mediated m6A modification, which consequently suppressed intracellular calcium concentration and ovarian cancer metastasis." (PMID 35869392, 2022).
ovarian carcinoma (continued). "Concerning ovarian carcinoma cells, TRPV6, TRPC3 and T-type calcium channel are found to be overexpressed leading to think that these proteins could be considered as therapeutic targets." (PMID 25627260, 2015).
atherosclerosis (11 papers, 2016 to 2024). A disease characterized by the build-up of fatty material and calcium deposition in the arterial wall resulting in partial or complete occlusion of the arterial lumen. "The Vazquez group used a mouse model of atherosclerosis and found that the deficiency of TRPC3 in bone marrow reduced the necrotic core of atherosclerotic plaques." (PMID 32872338, 2020). "TRPC3 has been documented to be implicated in atherosclerosis through regulating endothelium and macrophages." (PMID 29387339, 2018). "The present study was aimed at examining the impact of macrophage-specific loss of TRPC3 on typical features of advanced atherosclerotic lesions in a mouse model of atherosclerosis." (PMID 28186192, 2017). "Moreover, TRPC3 shows its impact on endothelial dysfunction and is responsible for causing apoptosis of macrophages related to the pathogenesis of atherosclerosis." (PMID 35303866, 2022). "It indicated that macrophage TRPC3 had different effects on atherosclerosis under different environmental stimuli." (PMID 37404813, 2023). "In atherosclerosis, macrophage TRPC3 channel activation enhances inflammation and the development of atherosclerotic plaques." (PMID 37588590, 2023). "The relevance of TRPC3 with atherosclerosis has also been verified by in vivo studies, where the process is associated with endoplasmic reticulum stress that is considered the primary mechanism of cell apoptosis in atherosclerotic plaques." (PMID 35303866, 2022). "It prevents diabetic cardiomyopathy by inhibiting NOX2/TrPC3-induced oxidative stress, and protects against atherosclerosis by reducing reactive oxygen species production and regulating smooth muscle proliferation." (PMID 35217815, 2022). "This work identified that genetically elevated TRPC3-mediated Ca2+ influx promoted atherosclerosis via increasing vascular cell adhesion molecule-1 and phospho-IkBα in the transgenic endothelium." (PMID 32872338, 2020). "miR-26a alleviated the development of atherosclerosis by regulating TRPC3, providing a potential target for atherosclerosis treatment." (PMID 29387339, 2018). "Additionally, studies in endothelial cells discovered that endothelial overexpression of the human TRPC3 channel increased the size and cellularity of advanced atherosclerotic lesions in mice model of atherosclerosis." (PMID 37588590, 2023). "The miR-26a alleviates the development of atherosclerosis by regulating TRPC3." (PMID 37588590, 2023). "In conclusion, our study demonstrated that miR-26a was downregulated in atherosclerosis and restoration of miR-26a expression alleviated the pathogenesis of atherosclerosis by targeting TRPC3, providing a new insight into the mechanism of miR-26a in the progression of atherosclerosis." (PMID 29387339, 2018). "Since TRPC6 was previously identified as a target of miR-26a in atherosclerosis development, we hypothesized whether miR-26a could also directly target TRPC3 to regulate the pathogenesis of atherogenesis." (PMID 29387339, 2018). "The future effort is required to investigate whether selective TRPC1/TRPC3 channel blockers can be clinically used for treating atherosclerosis in patients with high ox-LDL." (PMID 27472391, 2016). "In addition, TRPC3 is involved in the early and late pathological changes of atherosclerosis." (PMID 38255767, 2024). "Moreover, the anti-arteriosclerotic effects of miR-26a were mediated partially through the regulation of its target TRPC3, providing the evidence again that miR-26a may be a potential therapeutic target for atherosclerosis." (PMID 29387339, 2018). "Therefore, we hypothesized whether miR-26a could also target TRPC3 to regulate the progression of atherosclerosis." (PMID 29387339, 2018). "Altogether, these studies indicate that TRPC3/C6 and TRPV1/V4 in particular are involved in different aspects of atherosclerosis progression, while more data are needed to confirm the role of other TRPC and TRPV isoforms." (PMID 32854408, 2020).
atherosclerosis (continued). "In the study of human coronary artery endothelial cells (HCAEC), it was found that TRPC3 may mediate Ca2+ influx through the CAM/CAMK signaling pathway and activate NF-κB, and via NFκB the control of VCAM-1 expression in HCAEC is involved in the pathogenesis of atherosclerosis." (PMID 38255767, 2024).
melanoma (11 papers, 2018 to 2026). A malignant, usually aggressive tumor composed of atypical, neoplastic melanocytes. "In addition, the expression of TRPC3 has been associated with other skin diseases, such as melanoma, which exhibits an extremely poor prognosis owing to its rapidly progressive and highly metastatic nature." (PMID 34489697, 2021). "We confirmed the TRPC3 was abundantly expressed in human melanoma tissues according to a tissue microarray." (PMID 37759164, 2023). "For instance, SNHG5 facilitates the growth and invasion of melanoma cells by targeting miR-26a-5p and elevating TRPC3 expression." (PMID 35166647, 2022). "The pharmacological inhibition of TRPC3 by Pyr3, a pyrazol compound, was shown to decrease melanoma cell proliferation and migration, and knockdown of TRPC3 reduced melanoma cell proliferation." (PMID 34489697, 2021). "Moreover, LncRNA SNHG5 plays a critical role in the growth and invasion process of melanoma via the miR-26a-5p/TRPC3 signaling pathway." (PMID 35870973, 2022). "Transient receptor potential canonical 3 (TRPC3) is widely expressed in human melanoma." (PMID 36081847, 2022). "SNHG5 plays an analogous role in melanoma by regulating the miR-26a-5p/TRPC3 pathway." (PMID 33392203, 2020). "Pharmacological inhibition of TRPC3 by a pyrazole compound of Pyr3, decreased melanoma cell proliferation and migration, which indicated that TRPC3 plays an important role in melanoma growth, and may be a novel target for the treatment of melanoma in patients." (PMID 36081847, 2022). "In melanoma, the lncRNA SNHG5 was found to affect tumor development by regulating the miR-26a-5p/TRPC3 pathway." (PMID 35870973, 2022). "Furthermore, pro-metastatic phenotypes driven by SNHG5–miRNA interactions have been observed in melanoma and osteosarcoma, where SNHG5 promotes invasion via the miR-26a-5p/TRPC3 axis." (PMID 41550840, 2026). "Indeed, we confirmed that a pyrazole compound Pyr3, which is a TRPC3-selective inhibitor, suppressed SOCE in human melanoma cells (C81619 cells)." (PMID 37759164, 2023).
heart failure (10 papers, 2007 to 2024). Inability of the heart to pump blood at an adequate rate to meet tissue metabolic requirements. "The TRPC family of proteins (TRPC1-7) function as both homo- and hetero-tetramers, and both Trpc1 and Trpc3 as well as Trpc6 have been implicated in heart failure induced by pressure overload." (PMID 35096991, 2021). "TRPC3 channels have been shown to play a role in cardiac fibrosis and fibrosis-associated heart diseases, such as atrial fibrillation (AF) and heart failure induced by pressure overload." (PMID 31547577, 2019). "Several small compounds that inhibit TRPC3/6 channel activities directly or indirectly prevent pressure overload-induced heart failure in mice." (PMID 36289215, 2022). "The known main mechanism is involved in the calcineurin/NFAT signaling pathway to promote Ca2+ influx via TRPC3 and induces mechanical stress, hypertrophy, and heart failure." (PMID 31871548, 2019). "TRPC3 was found to positively regulate ROS signaling through increasing Nox2 protein stability by forming a protein complex with Nox2, supporting the pathological importance of TRPC3 in ROS-dependent heart failure." (PMID 28790356, 2017). "During heart failure progression, overexpression of NCX1 and TRPC3/NCX1 interaction are compensatory mechanisms that improve systolic function." (PMID 39590195, 2024). "As the inhibition of TRPC3, but not TRPC6, actually suppressed pressure overload-induced heart failure, oxidative modification of Gpx3 will be a novel biomarker for diagnosing the severity of maladaptive cardiac remodeling." (PMID 28790356, 2017).
atrial fibrillation (9 papers, 2015 to 2025). A disorder characterized by an electrocardiographic finding of a supraventricular arrhythmia characterized by the replacement of consistent P waves by rapid oscillations or fibrillatory waves that vary in size, shape and timing and are accompanied by an irregular ventricular response. "TRPC3 channels are involved in cardiac fibrosis and fibrosis-associated cardiac disorders, including atrial fibrillation and pressure overload-induced HF." (PMID 40149710, 2025). "Overall, the data suggest that TRPC3 is likely a potential therapeutic target for fibrosis-associated atrial fibrillation." (PMID 31547577, 2019). "TRPC3 channels mediating Ca2+ entry are up-regulated in clinical and experimental atrial fibrillation (AF), and are implicated in SAN dysfunction and atrioventricular block." (PMID 26793124, 2015). "TRPC3 channels have been shown to play a role in cardiac fibrosis and fibrosis-associated heart diseases, such as atrial fibrillation (AF) and HF induced by pressure overload." (PMID 36969589, 2023). "The mechanism by which atrial fibrillation increases TRPC3 expression is mediated by NFAT-induced downregulation of microRNA-26." (PMID 31547577, 2019). "TRPC3 blockade with Pyr3 also inhibited angiotensin-II-induced Ca2+ entry, proliferation, and differentiation of fibroblasts isolated from left atrial of electrically maintained atrial fibrillation in a dog model." (PMID 30881310, 2019). "TRPC3 expression is increased in the atria of patients with atrial fibrillation (AF) and in animal models of AF, whereby it likely induces fibroblast proliferation and differentiation." (PMID 32079284, 2020). "TRPC3 is upregulated in the atria of atrial fibrillation (AF) patients, and in atrial fibrillation goat, and dog models." (PMID 31547577, 2019). "In this study, we found that pacing-induced atrial fibrillation in angiotensin II treated mice was significantly reduced in mice lacking the TRPC3 gene (TRPC3−/− mice)." (PMID 25859221, 2015). "In vivo administration of the TRPC3 blocker Pyr3 reduces ECM protein expression and suppresses development of the AF substrate in the electrically-maintained dog model of atrial fibrillation." (PMID 31547577, 2019).